LINC00174 (long independently transcribed non-coding RNA 174)
Synonyms: NCRNA00174
Gene: Long non-coding RNA gene on chromosome 7 (66,376,044 to 66,493,606, reverse strand). Ensembl gene ENSG00000179406.
Diseases named in the same sentence as LINC00174 in open-access papers:
LINC00174 is named in the same sentence as 19 diseases in open-access papers, as found by Europe PMC text mining. Sharing a sentence is not in itself a finding about the gene and the disease. The quoted sentences say what the papers report.
glioma (12 papers, 2019 to 2024). A benign or malignant brain and spinal cord tumor that arises from glial cells (astrocytes, oligodendrocytes, ependymal cells). "The effect of LINC00174 on glioma progression was studied, and the underlying molecular mechanism by which LINC00174 regulated glioma cell phenotype was also investigated." (PMID 31492194, 2019). "Overexpression of linc00174 in glioma tissue and cell lines inhibits glycolysis in glioma cells and plays a suppressing role in tumor development." (PMID 38967893, 2024). "The high LINC00174 expression represented a disadvantageous consequence in glioma patients and LINC00174 exacerbated glioma cell invasion, migration and glycolysis." (PMID 33514309, 2021). "In glioma, LINC00174 accelerated carcinogenesis of glioma by promoting cell proliferation, migration, invasion and glycolysis of glioma cells; moreover, LINC00174 down-regulation decreases chemoresistance to temozolomide in human glioma cells." (PMID 34226413, 2021). "More recently, Shi and colleagues have reported that LINC00174 promotes cell proliferation, migration and apoptosis in part by the regulation of miR-152 in glioma." (PMID 33005104, 2020). "Previous studies have demonstrated that LINC00174 regulated cell proliferation, apoptosis, migration by sponging different miRNAs including miR-152 and miR-138 in glioma therapy." (PMID 33005104, 2020). "LINC00174 knockdown improves the response of human glioma cells to temozolomide by modulating the miR-138-5p/SOX9 axis." (PMID 33080570, 2020). "LINC00174 expression in glioma tissues and peritumoral brain edema (PTBE) tissues was examined by RT-qPCR and in situ hybridization." (PMID 31492194, 2019). "LINC00174 knockdown inhibited cell proliferation, migration, invasion and glycolysis of glioma cells, and LINC00174 exerted a tumorigenesis role." (PMID 31492194, 2019). "We found that LINC00174 was overexpressed in the glioma tissues and cells, and high expression of LINC00174 showed a unfavourable prognosis in glioma patients." (PMID 31492194, 2019). "We found that LINC00174 overexpression promoted cell migration and invasion of U251 and LN229 cells, and LINC00174 knockdown inhibited cell migration and invasion of glioma cells (P < 0.001)." (PMID 31492194, 2019). "The expression of LINC00174 in different stages of glioma samples was examined by RT-qPCR and ISH analysis." (PMID 31492194, 2019). "In the present study, we first identified the expression of LINC00174 in the glioma tissues and cells." (PMID 31492194, 2019). "LINC00174 plays an oncogenic role in several cancers, including colorectal cancer, renal clear cell carcinoma, hepatocellular carcinoma, breast cancer, glioma, osteosarcoma, thymic epithelial tumors, and lung cancer." (PMID 37633972, 2023). "LINC00174 can promote the development of glioma by downregulating the expression of mir-138-5p." (PMID 35127343, 2022). "Furthermore, overexpressed LINC00174 leads to an increased cell proliferation, tumor growth, migration, invasion and glycolysis of glioma cells." (PMID 33652661, 2021). "LINC00174 promotes glioma progression via miR-152-3p/SLC2A1 axis." (PMID 34671615, 2021). "LINC00174 accelerates glioma carcinogenesis via sponging miR-152-3p." (PMID 33652661, 2021). "Knockdown of LINC00174 by regulating miR-138-5p/SOX9 axis could decrease chemoresistance to TMZ in glioma." (PMID 34178658, 2021). "In the present study, we explored the expression of LINC00174 in glioma tissues and normal tissues." (PMID 31492194, 2019). "The results showed that LINC00174 was overexpressed in glioma cell lines (P < 0.001)." (PMID 31492194, 2019). "LINC00174 was overexpressed in glioma tissues and cell lines." (PMID 31492194, 2019). "High expression of LINC00174 predicted an unfavorable prognosis in glioma patients." (PMID 31492194, 2019). "LINC00174 predicted an unfavorable prognosis in glioma patients." (PMID 31492194, 2019).
glioma (continued). "The expression of LINC00174 in human astrocytes (NHA) and five glioma cell lines including U251, LN229, H4, SW1783, and A172 was also examined." (PMID 31492194, 2019). "LINC00174 accelerated carcinogenesis of glioma via sponging miR-1523-3p and increasing the SLC2A1 expression, which could be considered as a molecular target for glioma diagnosis and therapy." (PMID 31492194, 2019).
colorectal cancer (7 papers, 2019 to 2023). A primary or metastatic malignant neoplasm that affects the colon or rectum. "Recent studies have reported that LINC00174 is associated with the malignant pathological features of patients with colorectal cancer and that it promotes tumor progression and metastasis." (PMID 37448887, 2023). "In 2018, Do and Kim for the first time reported that abnormal expressions of LINC00174 are associated with the occurrence of colorectal cancer." (PMID 33005104, 2020). "Overexpression of LINC00174 promotes the proliferation, migration, and invasion of colorectal cancer cells by regulating Mir-1910-3p/TAZ and Mir-3127-5p/E2F7 signaling pathways." (PMID 34692467, 2021). "As shown in results, NKILA and LINC00174 were all higher expressed in colorectal cancer cell line HT29 compared to normal colonic epithelial cell line NCM460." (PMID 34692467, 2021). "Several researchers also suggested that LINC00174 played significant roles in the molecular pathogenesis of several cancers, including hepatocellular carcinoma and colorectal carcinoma." (PMID 32522293, 2020). "Colorectal cancer patients with overexpression of LINC00174 have a poor prognosis." (PMID 34692467, 2021). "LINC00174 and NKILA were expressed in the nucleus and cytoplasm of normal colonic epithelial cell line NCM460 and colorectal cancer cell lines HT29." (PMID 34692467, 2021). "However, at present, no study has found whether LINC00174 and NKILA can affect the occurrence and development of colorectal cancer through autophagy, which will also be the focus of our follow-up research." (PMID 34692467, 2021).
thymic epithelial tumors (4 papers, 2020 to 2023). "LINC00174 involved in cell migration and lipid metabolism, and is a novel prognostic factor in thymic epithelial tumors." (PMID 34226413, 2021). "To explore the biological role of LINC00174 in thymic epithelial tumors, we first evaluated cell proliferation and migration ability after LINC00174 silencing." (PMID 33161413, 2020). "This study suggests as LINC00174 expression may become a valuable prognostic biomarker, opening the possibility to new potential therapeutic targets clinically relevant for treatment of thymic epithelial tumors." (PMID 33161413, 2020). "LINC00174 (ENSG00000179406) is overexpressed in liver cancer, glioblastoma, and thymic epithelial tumors and exerts a cancer-promoting function." (PMID 37448887, 2023).
colon cancer (1 paper, 2023). "miR-2467-3p overexpression blocked the promoting effects of LINC00174 on inflammation, suggesting that the mechanism by which LINC00174 promotes inflammation in colon cancer is inseparable from miR-2467-3p at the in vivo level." (PMID 37448887, 2023). "Using the colon cancer samples in TCGA database, LINC00174 was found to be positively correlated with ENO3 (r = 0.458, P < 0.001)." (PMID 37448887, 2023). "LINC00174 promotes the glycolysis, inflammation, proliferation, migration, and invasion of colon cancer cells and inhibits apoptosis." (PMID 37448887, 2023). "Next, to analyze the mechanism by which LINC00174 promotes colon cancer, TCGA database was used to identify ENO3, which is positively correlated with LINC00174 in colon cancer tissues." (PMID 37448887, 2023). "The effects of LINC00174 overexpression and silencing on the biological behavior of and inflammation in colon cancer cells were analyzed via transfection experiments." (PMID 37448887, 2023). "LINC00174 can promote colon cancer cell glycolysis, inflammation, proliferation, migration, and invasion and inhibit apoptosis." (PMID 37448887, 2023). "Taken together, the results suggest that the function of LINC00174 in regulating colon cancer is inseparable from that of miR-2467-3p." (PMID 37448887, 2023). "Furthermore, the overexpression of LINC00174 in colon cancer cell lines promoted the proliferation, migration, and invasion of colon cancer cells and inflammation but inhibited apoptosis." (PMID 37448887, 2023). "Furthermore, in vitro experiments using colon cancer cell lines revealed that LINC00174 overexpression promotes colon cancer cell proliferation, migration, invasion, and inflammation and inhibits apoptosis." (PMID 37448887, 2023). "This suggests that LINC00174 plays a positive role in colon cancer." (PMID 37448887, 2023). "However, LINC00174 overexpression not only promoted glucose uptake and increased lactate accumulation in colon cancer cells but also blocked the inhibitory effects of miR-2467-3p on glycolysis." (PMID 37448887, 2023). "LINC00174 expression was significantly increased in colon cancer tissues." (PMID 37448887, 2023). "LINC00174 was positively correlated with ENO3 in colon cancer tissues." (PMID 37448887, 2023). "The expression of LINC00174 and ENO3 in colon cancer tissues, its relationship with survival rate, and correlation were analyzed using bioinformatic analysis." (PMID 37448887, 2023).
rectal adenocarcinoma (1 paper, 2021). "In order to explore the molecular mechanism of LINC00174 functioning, we predicted 81 possible miRNAs bound by LINC00174 through the starBase website, and obtained 132 miRNAs with low expression in rectal adenocarcinoma through the TCGA database." (PMID 34226413, 2021). "In addition, we obtained 7 miRNAs that bind to LINC00174 and are lowly expressed in rectal adenocarcinoma through bioinformatics analysis." (PMID 34226413, 2021).
thymic carcinoma (1 paper, 2020). Thymic carcinoma (TC) is a type of thymic epithelial neoplasm characterized by a high malignant potential. "To address this, we first overexpressed or inhibited miR-145-5p in thymic carcinoma TC1889 cells and observed, respectively, the downregulation or the upregulation of LINC00174 and LINC00174-related signature, confirming that they depend on miR-145-5p activity." (PMID 33161413, 2020).
thymic tumor (1 paper, 2020). "We observed an upregulation of LINC00174 in thymic tumor tissue compared to normal tissue, and high levels of LINC00174 associated to poor patients’ prognosis." (PMID 33161413, 2020). "We confirmed that LINC00174 and LINC00174-related signature are upregulated in thymic tumor samples and primary cells compared to normal counterparts." (PMID 33161413, 2020).
thymoma (1 paper, 2020). A neoplasm arising from the epithelial cells of the thymus. "By transwell cell migration assay, we observed that silencing of LINC00174 significantly reduced cell migration in TC1889 cell line and in thymoma primary cells." (PMID 33161413, 2020).
cancer (7 papers, 2019 to 2024). A tumor composed of atypical neoplastic, often pleomorphic cells that invade other tissues. "LINC00174 mainly acts as an oncogene in cancer and is upregulated in OC; its knockdown inhibited the proliferation and migration, and promoted apoptosis of OC cells." (PMID 37633972, 2023). "We first reviewed the role of LINC00174 in cancer in previous literature reports and observed that it mainly acts as an oncogene in cancer." (PMID 37633972, 2023). "We also reviewed reports on the role of LINC00174 in cancer." (PMID 37633972, 2023). "LINC00174 plays a pro-cancer role by regulating different functions of cancer cells." (PMID 34226413, 2021). "Altogether these data indicate that both genes could contribute to increase phenotype of cancer and as LINC00174’s role in cancer might be mediated by action of miR-145-5p on target genes, involved in different cellular pathway, as SCD5." (PMID 33161413, 2020). "Therefore, LINC00174 may play a critical role in regulating glucose metabolism and cancer cell proliferation by modulating miR-2467-3p expression and ENO3 protein levels." (PMID 37448887, 2023). "However, the difference is that heterologous overexpression of LINC00174 also accelerated the migration and invasion ability of CRC cells, and may promote EMT protein and E2F7 by competitively binding miR-3127-5p to play a cancer-promoting role in CRC." (PMID 34226413, 2021). "Therefore, we suspected that LINC00943, LINC00174, DSCAM-AS1, MAGI1-IT1, MIR4458HG and LINC01133 may have similar regulatory roles in the proliferation and differentiation of stromal and neutrophil cells as those in the proliferation and differentiation of cancer cells." (PMID 38919957, 2024).
tumor (7 papers, 2019 to 2023). "The tumor volume and mass of the mice in the LINC00174+mimic group were significantly lower than those of the mice in the LINC00174+mimic NC group and significantly higher than those of the mice in the NC+mimic group." (PMID 37448887, 2023). "LINC00174 overexpression increased tumor volume and mass by approximately 1.8-fold, whereas miR-2467-3p overexpression inhibited tumor growth to half of that observed in the NC+mimic NC group." (PMID 37448887, 2023). "Based on this, we collected 80 clinical samples of CRC patients, and found that the level of LINC00174 was elevated in tumor tissue (p < 0.001)." (PMID 34226413, 2021). "Moreover, LINC00174 overexpression reversed the inhibitory effects of ENO3 protein levels on tumor tissues via miR-2467-3p." (PMID 37448887, 2023). "LINC00174 promoted glycolysis and tumor progression by targeting miR-152-3p/SLC2A1 axes." (PMID 31492194, 2019). "Moreover, downregulation of LINC00174 also inhibited tumor volume and delayed the tumor growth in vivo." (PMID 31492194, 2019).
LINC00174 also shares sentences with these, for which no sentence is quoted: hepatocellular carcinoma (3 papers); glioblastoma (2); osteosarcoma (2); breast carcinoma (1); liver cancer (1); low grade glioma (1); lung carcinoma (1); ovarian carcinoma (1); renal clear cell carcinoma (1).